IRF6 (interferon regulatory factor 6)
Diseases named in the same sentence as IRF6 in open-access papers (continued):
Sharing a sentence is not in itself a finding about the gene and the disease.
ischemic stroke (3 papers, 2019 to 2025). A stroke disorder caused by obstruction of blood flow to the brain, due to thrombotic (local blood clot formation) or embolic (due to a blood clot or other material traveling from another site) event. "The current state of the literature provides significant evidence of a statistically relevant association between SNPs of the IRF6 gene and ischemic stroke, further corroborated by recent studies identifying a role for IRF6 as a regulator of PPARγ in the post-ischemic response." (PMID 40149423, 2025). "In addition, other paralogs of IRF6, such as IRF4, IRF5, IRF8, and IRF9, have been linked to neuronal survival following ischemic stroke." (PMID 40149423, 2025). "We believe it is worth reporting a case in the literature where a variant of the IRF6 gene is phenotypically expressed, ischemic stroke occurred, and no clearly recognized underlying cause can be identified to explain the clinical presentation." (PMID 40149423, 2025). "Notably, IRF6 expression was found to differ between ischemic stroke cases and controls, suggesting that this gene might contribute to stroke susceptibility." (PMID 40149423, 2025).
pancreatic ductal adenocarcinoma (3 papers, 2019 to 2025). An infiltrating adenocarcinoma that arises from the epithelial cells of the pancreas. "Here, in a pancreatic ductal adenocarcinoma model of acquired resistance to immunotherapy, the authors show that plasticity-induced repression of Irf6 is associated with tumor cell-intrinsic resistance to cytotoxic T-cell activity." (PMID 38378697, 2024). "In a mouse model for pancreatic ductal adenocarcinoma, acquired resistance of tumor cells to immune checkpoint inhibition was shown to be mediated by decreased expression of IRF6, which results in an inability of tumor cells to be killed by TNF-α released from immune cells." (PMID 40569988, 2025). "To evaluate if ELF3 directly regulate IRF6 expression or not, we firstly analyzed the only available chip-seq data of ELF3 antibody in the pancreatic ductal carcinoma, which obtained from the online website of Cistrome." (PMID 31019894, 2019).
renal carcinoma (3 papers, 2021 to 2023). A carcinoma arising from the epithelium of the renal parenchyma or the renal pelvis. "A recent study also pointed out that IRF6 expression was downregulated in renal carcinoma tissues and decreased IRF6 expression was associated with poor prognosis." (PMID 34659554, 2021). "High expression of IRF6 inhibited proliferation, invasion, migration and metastasis of renal carcinoma cells." (PMID 36798768, 2023). "The database predicted down-regulated IRF6 expression in renal carcinoma tissues and its correlation with poor prognosis." (PMID 33941190, 2021). "Interestingly, KIF20A could partially reverse the effects of IRF6 on renal carcinoma cells." (PMID 36798768, 2023). "ChIP experiment verified the combination of IRF6 and KIF20A promoters, indicating that KIF20A was a target of IRF6 in renal carcinoma." (PMID 36798768, 2023). "Through GEPIA, HAP and other databases, we found that the expression of IRF6 and KIF20A in ccRCC is likely to be correlated with the pathological stage and overall survival rate of renal carcinoma patients." (PMID 33941190, 2021). "HPA database showed that the IHC results of IRF6 in renal carcinoma were negative." (PMID 33941190, 2021).
steatosis (3 papers, 2024 to 2026). Increased lipid within the cytoplasm of cells. "In the HFD-induced NAFLD model, hepatic IRF6 was inhibited by promoter hypermethylation, and hepatocyte-specific transgenic mice overexpressing IRF6 exhibited attenuated steatosis and metabolic disease." (PMID 38999981, 2024). "However, one study mentioned that in their model, Irf6 levels were significantly downregulated in HFD-induced steatosis and the overexpression of Irf6 in hepatocytes attenuated lipid accumulation." (PMID 41153338, 2025). "Additional evidence demonstrates that IRF5, IRF6, and IRF8 are also play key roles in hepatocytes: IRF5 mediates Fas-induced apoptosis, IRF6 suppresses PPARγ to reduce lipid accumulation, and IRF8 aggravates steatosis through a BMAL1/PPARγ axis." (PMID 41614922, 2026).
bladder cancer (2 papers, 2021). "Although IRF6 promoter has low methylation (β-value < 0.5) in this patient cohort, high-staged bladder cancer has higher methylation than those with lower stage." (PMID 33874979, 2021). "As expected, high-staged bladder cancer patients demonstrated a lower IRF6 expression than low-staged patients." (PMID 33874979, 2021). "Taken together, this clinical data suggested that DNA methylation may be partially responsible for the down-regulation of IRF6 in bladder cancer patients." (PMID 33874979, 2021). "Finally, we examined expression and promoter methylation of IRF6 in TCGA bladder cancer cohort." (PMID 33874979, 2021).
endometriosis (2 papers, 2023 to 2025). The growth of functional endometrial tissue in anatomic sites outside the uterine body. "Based on our previous studies and the JASPAR software analysis, we hypothesize that the transcription factor IRF6 may regulate BST2 expression in endometriosis by directly binding to its promoter region." (PMID 37143676, 2023). "Overall, the data presented in this study reveal the transcription factor IRF6-associated regulation of BST2 expression, the pathological function of BST2 in endometriosis, novel signaling pathway mediated by BST2, and the therapeutic potential of targeting BST2 for the treatment of endometriosis." (PMID 37143676, 2023). "IRF6 regulates the high expression of BST2, which further activates the NF-κB signaling pathway to induce proliferation, migration, apoptosis and lymphangiogenesis in endometriosis." (PMID 37143676, 2023).
head and neck squamous cell carcinoma (2 papers, 2018 to 2021). A squamous cell carcinoma that arises from any of the following anatomic sites: lip and oral cavity, nasal cavity, paranasal sinuses, pharynx, larynx, and salivary glands. "In addition, IRF6 has been found mutated in head and neck squamous cell carcinoma and IRF6 is often lost or downregulated in many solid cancers." (PMID 34660580, 2021). "Furthermore two independent studies showed that IRF6 gene mutations were associated to head and neck squamous cell carcinomas." (PMID 30089163, 2018).
neuroblastoma (2 papers, 2023 to 2025). Neuroblastoma (NB) is the most common solid, extracranial childhood tumor. "Collectively, these results suggest that IRF6 is downregulated in high-risk neuroblastoma patients and correlated with poor survival." (PMID 40796729, 2025). "The results provided evidence that IRF6 expression was low in high-risk neuroblastoma patients and was related to poor survival." (PMID 40796729, 2025). "Our results revealed that decreased IRF6 expression is associated with an inferior prognosis in neuroblastoma patients, providing a predictive index for curative effects on neuroblastoma." (PMID 40796729, 2025). "Kaplan‒Meier survival analysis revealed that low IRF6 expression was associated with a poor overall and event-free survival in neuroblastoma patients, based on the GSE16476 and Cangelosi786 datasets." (PMID 40796729, 2025). "Low IRF6 expression was further determined to be associated with dismal survival in neuroblastoma patients." (PMID 40796729, 2025). "To the best of our knowledge, this is the first report on the decreased expression of IRF6 in neuroblastoma cells, and we demonstrated that IRF6 overexpression suppresses glycolysis-mediated tumor cell proliferation." (PMID 40796729, 2025). "Conversely, IRF6 knockdown in neuroblastoma cell lines SH-SY5Y and SK-N-SH using IRF6 siRNAs or a control plasmid led to increased cell growth." (PMID 40796729, 2025). "In our study, IRF6 was also found to be decreased in neuroblastoma, with its overexpression inhibiting glycolysis-mediated tumor cell growth." (PMID 40796729, 2025). "To further determine the clinical significance of the IRF6 protein in neuroblastoma, we performed IHC staining with an antibody against IRF6, which showed positive staining in the cytoplasm, in a cohort of 126 neuroblastoma tissues." (PMID 40796729, 2025). "We subsequently analyzed IRF6 expression and found it to be consistently downregulated in neuroblastoma tissues compared to that in normal adrenal gland tissues." (PMID 40796729, 2025). "The overexpression of IRF6 markedly decreased the cell viability and proliferation rate of the indicated neuroblastoma cells." (PMID 40796729, 2025). "To elucidate the mechanism by which IRF6 expression is kept low, thereby affecting glycolysis-mediated tumorigenesis in neuroblastoma cells, we analyzed the DEGs between neuroblastoma and adrenal gland tissues using the TARGET and GTEx datasets (UCSC Xena)." (PMID 40796729, 2025). "Our study revealed that PGM1 serves as a target for IRF6-mediated glycolysis and tumorigenesis in neuroblastoma cells." (PMID 40796729, 2025). "To further confirm that IRF6 regulates the growth of neuroblastoma cells in vivo, we established a tumor-bearing model by the subcutaneous injection of SK-N-BE2 cells with stable overexpression of IRF6 into NCG mice (n = 5 per group)." (PMID 40796729, 2025). "Patients were divided into high- or low-IRF6 expression groups, and Kaplan‒Meier analysis similarly revealed that neuroblastoma patients with low IRF6 expression had worse overall and event-free survival than those with high IRF6 expression." (PMID 40796729, 2025). "Consequently, IRF6 overexpression inhibits glycolysis and eventually represses tumor cell proliferation in neuroblastoma." (PMID 40796729, 2025). "IRF6 has been identified as a prognostic marker in several cancers, but its prognostic value in neuroblastoma remains unknown." (PMID 40796729, 2025). "To identify key genes that IRF6 likely interacts with and are influenced by IRF6 expression in the context of neuroblastoma metabolism, we intersected the downregulated DEGs with those involved in the glycolysis/gluconeogenesis pathways, resulting in a set of 18 genes." (PMID 40796729, 2025). "Notably, neuroblastoma patients with PGM1 high/IRF6 low integrated expression had the worst overall and event-free survival." (PMID 40796729, 2025).
neuroblastoma (continued). "Additionally, given that ubiquitination is a major mechanism promoting protein degradation, we hypothesized that specific E3 ligases bind to IRF6, promoting its ubiquitination and degradation in neuroblastoma." (PMID 40796729, 2025). "In the present study, we hypothesized that IRF6 acts as a tumor suppressor in neuroblastoma." (PMID 40796729, 2025). "However, the role of IRF6 in neuroblastoma is yet to be fully elucidated." (PMID 40796729, 2025). "Therefore, we investigated whether IRF6 overexpression inhibits the expression of downstream targets that attenuate glycolysis in neuroblastoma cells." (PMID 40796729, 2025). "Additionally, IRF6 expression was diminished in neuroblastoma due to E3 ligase TRIM59-mediated polyubiquitination, and may reverse the promoting effect of TRIM59 overexpression on cell proliferation and glycolysis." (PMID 40796729, 2025). "Based on the mechanism of IRF6 regulation by TRIM59-mediated ubiquitination, we assessed the functional phenotype of neuroblastoma cells after altering the expression levels of TRIM59 and IRF6." (PMID 40796729, 2025). "Given the significant roles of IRF6 and PGM1 in glycolysis regulation and neuroblastoma progression, we analyzed their impact on patient survival in our cohort." (PMID 40796729, 2025). "In this study, we first revealed that IRF6 acts as a potent inhibitor of tumor cell growth by targeting PGM1 transcription and modulating the cellular glycolytic process in neuroblastoma." (PMID 40796729, 2025). "Since IRF6 has not yet been previously studied in neuroblastoma, we selected it for further investigation." (PMID 40796729, 2025). "Interestingly, IRF6 targets the PGM1 promoter region and weakens its transcriptional activity in neuroblastoma." (PMID 40796729, 2025). "Moreover, IRF6 expression was downregulated due to an increased level of ubiquitination mediated by the E3 ligase TRIM59, which correlated with unfavorable outcomes in neuroblastoma patients." (PMID 40796729, 2025). "In our study, we found that IRF6 directly interacted with the PGM1 promoter, inhibiting its transcription; subsequently, the downregulation of PGM1 inhibited glycolysis-mediated tumor cell proliferation in neuroblastoma, highlighting the role of PGM1 in facilitating the progression of neuroblastoma." (PMID 40796729, 2025).
Pancreatic Carcinoma (2 papers, 2022). "According to the data of Huadong’s study, IRF6 was upregulated in Pancreatic Carcinoma tissues and the FC is 2.43." (PMID 35012444, 2022).
Pierre-Robin sequence (2 papers, 2017 to 2020). Pierre Robin malformation is a sequence of developmental malformations characterized by micrognathia (mandibular hypoplasia), glossoptosis and cleft palate. "According to HGMD®, there are currently 351 described pathogenic IRF6 variants that either cause non-syndromic CLP, or the rare diseases Pierre Robin Sequence (OMIM # 261800), VWS or the related PPS." (PMID 33117810, 2020).
rectal cancer (2 papers, 2017 to 2019). A primary or metastatic malignant neoplasm that affects the rectum. "In particular, the authors demonstrated that the IRF2 mutational status is associated with both colon and rectal cancer, whereas mutations in other genes involved in IFN signaling pathway were uniquely associated with colon (IFN-γ and IRF3) or rectal cancer (IFNGR1, IFNGR2, IRF4, IRF6, and IRF8)." (PMID 28798748, 2017).
Stroke (2 papers, 2017 to 2025). Sudden impairment of blood flow to a part of the brain due to occlusion or rupture of an artery to the brain. "The current findings should aid future researchers in better characterizing IRF6 as a novel therapeutic target for modulating PPARγ-associated signaling cascades for purposes of stroke treatment." (PMID 28526834, 2017). "Further investigation into IRF6 and other PPARγ co-regulators should provide additional insights into PPARγ’s cytoprotective role in the cerebrovascular endothelium following stroke." (PMID 28526834, 2017). "Further research on IRF6 and other co-regulators of PPARγ could offer a deeper understanding of PPARγ’s protective effects in the cerebrovascular endothelium following a stroke." (PMID 40149423, 2025).
acute myeloid leukemia (1 paper, 2026). Acute myeloid leukemia (AML) is a group of neoplasms arising from precursor cells committed to the myeloid cell-line differentiation. "Erythroid acute myeloid leukemia (AML) cell line OCI-M2 expresses a particular oncogenic network: IRF6, in concert with ETV2 and HEY1, aberrantly activates NKL homeobox gene NKX2-4, which in turn represses megakaryocytic lineage factor FLI1." (PMID 41892358, 2026).
alcohol addiction (1 paper, 2025). "Nek3, Ntf3, Cux1, and Irf6 expression changes were shared across at least three tissues and may be potential biomarkers of alcohol addiction." (PMID 41153338, 2025).
brain cancer (1 paper, 2022). A primary or metastatic malignant neoplasm affecting the brain. "However, we obtained further evidence of reduced IRF6 levels in brain cancer compared to control by the HPA database and our own IHC analysis." (PMID 36457487, 2022). "We also screened a panel of brain cancer cell lines for IRF6 and GRHL3." (PMID 36457487, 2022). "IRF6 was not detectable in 4/5 brain cancer cell lines tested, while GRHL3 levels were variable, ranging from not detectable (e.g., Hs683, T98G) to high expression in LN319." (PMID 36457487, 2022).
colorectal tumors (1 paper, 2025). "In addition, a variant in the 3’ UTR of IRF6 that decreases its expression was shown to be associated with decreased survival and enhanced M2 macrophage infiltration of colorectal tumors in humans, and IRF6 was found to promote M2 macrophage polarization in vitro." (PMID 40569988, 2025).
craniosynostosis (1 paper, 2017). Craniosynostosis is defined as the premature fusion of one or more cranial sutures leading to secondary distortion of skull shape resulting in skull deformities with a variable presentation. "Compared to skeletal preparation of wild type littermate pups, we found that loss of Irf6 causes mandibular hypoplasia and craniosynostosis." (PMID 28769044, 2017). "In the mouse, we found that loss of Irf6 causes craniosynostosis and mandibular hypoplasia." (PMID 28769044, 2017). "First, Irf6 null pups display mandibular hypoplasia and craniosynostosis although IRF6 is not expressed in early mandible or in skull bones, suggesting a non-cell-autonomous effect." (PMID 28769044, 2017).
cutaneous squamous cell carcinoma (1 paper, 2021). "Markedly decreased IRF6 expression is found in cutaneous squamous cell carcinoma and has been shown to promote the invasion and growth of cancer cells." (PMID 33941190, 2021).
ductal carcinoma (1 paper, 2024). "This immunohistochemical analysis indicated that TNFAIP6, IFRD1, and IRF6 protein expression intensity was positive in normal breast tissue and ductal carcinoma." (PMID 39765744, 2024). "The immunohistochemical analysis indicated that IRF6 protein expression was positive in normal breast tissue and ductal carcinoma." (PMID 39765744, 2024).
esophageal squamous cell carcinoma (1 paper, 2019). Esophageal squamous cell carcinoma (ESCC) is a type of esophageal carcinoma (EC) that can affect any part of the esophagus, but is usually located in the upper or middle third. "Interestingly, analysis of microarray data of NOTCH3 knockdown (GSE27424) showed that silencing NOTCH3 results in a significant increase of ZEB1 and a significant decrease of IRF6 in esophageal squamous cell carcinoma." (PMID 31019894, 2019).
gingivitis (1 paper, 2019). A disorder involving inflammation of the gums; may affect surrounding and supporting structures of the teeth. "It has been recently found that IRF6 (IFN regulatory factor) is the key regulator for the expression of IL-36γ through oral epithelial cells in response to gingivitis." (PMID 35919625, 2019).
Hepatic steatosis (1 paper, 2025). Steatosis is a term used to denote lipid accumulation within hepatocytes. "Our results indicated that GA downregulated the PPARγ signaling by increasing hepatic IRF6 levels, which then weakened lipid synthesis and accumulation by downregulating lipogenesis-related factors, ultimately relieving hepatic steatosis and liver damage." (PMID 40235530, 2025). "Previous studies have demonstrated that hepatic IRF6, a transcription factor, serves as a critical factor in liver steatosis and exerts its role through negative regulation of PPARγ." (PMID 40235530, 2025).
kidney chromophobe (1 paper, 2021). "Through GEPIA database, we predicted the expression of IRF6 in the tissues of patients with kidney chromophobe (KICH), kidney renal clear cell carcinoma (KIRC), and kidney renal papillary cell carcinoma (KIRP)." (PMID 33941190, 2021).
lentivirus infection (1 paper, 2015). Virus diseases caused by the Lentivirus genus. "Irf6 mRNA level in palatal shelves was analyzed at 6, 12, and 18 hours by quantitative RT-PCR after lentivirus infection." (PMID 26240017, 2015). "When shTgfβ3 lentivirus infection was carried out, it was found to block 60% of TGFβ3 protein expression and there was a decrease in the expression of IRF6 in palatal shelves by 70%." (PMID 26240017, 2015).